PHGDH (phosphoglycerate dehydrogenase)
Diseases named in the same sentence as PHGDH in open-access papers (continued):
Sharing a sentence is not in itself a finding about the gene and the disease.
cancer (continued). "Collectively, these results suggest that PHGDH expression is involved in increased cancer aggressiveness and promotes an enrichment in the stemness properties of CRC cell lines." (PMID 40640948, 2025). "Furthermore, a recent study revealed heterogeneous PHGDH expression in primary tumors to be associated with increased metastasis; low PHGDH protein expression promotes metastasis through a noncatalytic mechanism, offering new insights into the role of serine metabolic enzymes in cancer progression." (PMID 40552664, 2025). "The NAD+/NADH ratio was also elevated in cancer cells with higher PHGDH protein levels upon serine depletion (A375, PHGDH-overexpressing MDA-MB-231)." (PMID 40654753, 2025). "Specifically, PHGDH expression is dynamically regulated during different stages of tumor progression, promoting cancer aggressiveness." (PMID 40640948, 2025). "This destabilization of PHGDH diminishes endogenous serine production, shifting cancer cells toward increased exogenous serine uptake to fuel critical pathways like sphingolipid biosynthesis." (PMID 40475404, 2025). "This pathway consists of three sequential enzymes: phosphoserine aminotransferase 1 (PSAT1), phosphoserine phosphatase (PSPH), and PHGDH, the rate‐limiting enzyme extensively studied as a cancer therapy target." (PMID 40552664, 2025). "In this review, we thoroughly examine the pivotal role of PHGDH and its implications for cancer treatment." (PMID 38945960, 2024). "Cancer cells that overexpress PHGDH have a high inclination towards serine synthesis, leading to tumorigenesis through upregulation of serine biosynthesis pathways." (PMID 38816356, 2024). "This study investigates the prognostic value of phosphoglycerate dehydrogenase (PHGDH) in HGSOC which has been linked to metabolic reprogramming and recurrences in other cancers." (PMID 38920311, 2024). "This detailed review explores the role of 3-phosphoglycerate dehydrogenase, an enzyme, in cancer, particularly its role in serine creation and its potential as a treatment target." (PMID 38945960, 2024). "PHGDH not only influences the various cancer types mentioned earlier but also plays a crucial role in tumor metastasis." (PMID 38945960, 2024). "This increase aligns with evidence demonstrating that patients with a high PHGDH level have a shorter survival time than those with a low PHGDH level, suggesting the possible involvement of PHGDH in cancer progression in NSCLC patients." (PMID 38945960, 2024). "In this review, the structural aspects of PHGDH and its involvement in one-carbon metabolism are investigated, and PHGDH is proposed as a potential therapeutic target in diverse cancers." (PMID 38945960, 2024). "By elucidating how PHGDH expression promotes cancer growth, the goal of this review is to provide insight into innovative treatment strategies." (PMID 38945960, 2024). "With insights drawn from an in-depth analysis of existing research on metabolic processes, our primary focus is on elucidating the importance of PHGDH across various cancers to propose its potential as a promising therapeutic target." (PMID 38945960, 2024). "Targeting PHGDH in cancer cells overexpressing PHGDH inhibited cancer cell growth in vitro and in vivo." (PMID 38710705, 2024). "Elevated PHGDH expression in cancer correlates with increased cancer progression, increased metastasis rates and decreased patient survival rates." (PMID 38945960, 2024). "Together, these data indicate that Ser consumption by cancer cells inversely correlates with PHGDH status and a decreased Ser content CM results in a more prominent diameter reduction following incubation with myotubes." (PMID 39706853, 2024). "ASS1 knockout or knockdown enhanced PHGDH protein stabilization to increase serine synthesis and promote cancer cell proliferation and, consequently tumorigenesis, providing a novel anticancer mechanism of ASS1 in TNBC." (PMID 38710705, 2024).
cancer (continued). "Phosphoglycerate dehydrogenase (PHGDH), the enzyme that catalyses the first step in serine biosynthesis, is often upregulated in cancer cells." (PMID 39796683, 2024). "PHGDH is amplified in the malignant tumor and is essential for nucleotide production and cell proliferation in highly aggressive brain metastatic cells." (PMID 39351147, 2024). "Serine metabolism has emerged as a crucial participant in cancer biology, and PHGDH, the rate-limiting enzyme of de novo serine biosynthesis has garnered attention as a therapeutic target." (PMID 38690164, 2024). "In metabolically active cancer cells these processes are often dysregulated through oncogenic activity by enzymes such as Phosphoglycerate Dehydrogenase (PHGDH), Phosphoserine Aminotransferase 1 (PSAT-1) and Phosphoserine Phosphatase (PSPH)." (PMID 38702616, 2024). "While these interactions were found in both, normal and cancer cells from the lung, serine de novo synthesis and serine to glycine conversion were consistently elevated in the investigated (PHGDH positive) cell lines compared to normal BEC cells." (PMID 38515202, 2024). "Studies have revealed that inhibitors targeting PHGDH suppress the proliferation and reduce the growth of xenografts, especially in PHGDH‐dependent cancer cell lines." (PMID 38279895, 2024). "Ultimately, these characteristics allow PHGDH to not only influence the growth and progression of cancer but also play an important role in metastasis and drug resistance." (PMID 38945960, 2024). "Elevated PHGDH activity in diverse cancer cells is mediated through genetic amplification, posttranslational modification, increased transcription, and allosteric regulation." (PMID 38945960, 2024). "The SSP is frequently altered in cancer and PHGDH expression emerged to be very heterogeneous within a single tumor and among various tumor models, resulting a strong diversity in exogenous Ser addiction." (PMID 39706853, 2024). "For example, some cancer cells amplify the enzyme regulating the serine synthesis pathway (phosphoglycerate dehydrogenase) to obtain serine for de novo synthesis of purines and thymidine." (PMID 38646957, 2024). "PHGDH is known to be a substantial contributor to the importance of this pathway in cancer growth because PHGDH plays the most important role in serine production." (PMID 38945960, 2024). "Preclinical studies targeting PHGDH have shown promising results in inhibiting the growth of cancers via amplification of PHGDH." (PMID 38409249, 2024). "Activation of serine biosynthesis contributes to cancer cell proliferation, and overexpression of PHGDH has been observed in various cancers." (PMID 38874588, 2024). "3-Phosphoglycerate dehydrogenase (PHGDH) is known to play important roles in cancer progression and migration." (PMID 38945960, 2024). "Increased PHGDH activity in various cancer cells is mediated through genetic amplification, posttranslational modification, enhanced transcription, and allosteric regulation." (PMID 38945960, 2024). "Inhibition of the PHGDH activity is thought to be an attractive approach for novel anti-cancer therapy." (PMID 39257399, 2024). "In colorectal cancer, PHGDH inhibition cooperates with serine and glycine depletion to inhibit 1C metabolism, global protein synthesis and cancer growth." (PMID 38115544, 2024). "Subsequently, we subjected the pull-down products to silver staining and LC-MS/MS analysis, and one cancer-related protein, PHGDH, particularly piqued our interest." (PMID 39223162, 2024). "Numerous studies have consistently revealed significant upregulation of PHGDH expression across various cancer types, in which it is correlated with tumor aggressiveness." (PMID 38945960, 2024). "The roles of PHGDH in various cancer types point toward promising options for novel treatment strategies." (PMID 38945960, 2024). "In the context of various cancer treatments and considering PHGDH expression, combining PHGDH inhibition with other therapies is one such strategy." (PMID 38945960, 2024).
cancer (continued). "The expression of PHGDH in normal tissues adjacent to cancer and UCEC tissues were further compared." (PMID 36803157, 2023). "Serine-biosynthesis pathway plays a key role in cancer, and high PHGDH expression maintains a high serine synthesis flux." (PMID 36984785, 2023). "These molecules inhibit the proliferation of PHGDH-dependent cancer cells, suggesting the potential role of serine biosynthesis in one-carbon unit metabolism." (PMID 37664062, 2023). "Here, we explored the anti-cancer effects of the pyruvate kinase (PK) M2 inhibitor PKM2-IN-1 alone or in combination with the phosphoglycerate dehydrogenase (PHGDH) inhibitor NCT-503 in human NSCLC A549 cells in vitro and in vivo." (PMID 37284309, 2023). "Because the abnormal growth and proliferation characteristic of various cancer cells is accompanied by increased PHGDH activity and expression, PHGDH has been considered a promising anti-cancer drug target." (PMID 37687259, 2023). "Distinct studies demonstrate that PHGDH upregulation and serine biosynthesis can play a role in sustaining cancer cell growth and transformation." (PMID 37946250, 2023). "Increased intracellular serine pools in cancer cell lines appeared to result from the over-expression of PHGDH and PSPH, which are involved in intracellular serine biosynthesis." (PMID 37299011, 2023). "In tumors of the metabolic molecular group, the high expression of genes that play an essential role in cancer-specific metabolic reprogramming, such as PHGDH, has been observed." (PMID 36831448, 2023). "The combination of perhexiline with a PHGDH small molecule inhibitor (NCT-503) resulted in significant synergistic cell death in vitro and in vivo, providing preclinical justification for a dual metabolism-based combination therapy for PHGDH-high cancers." (PMID 37110858, 2023). "PHGDH knockdown or inhibitor markedly restrains the growth of these PHGDH-overexpressing cancers, suggesting PHGDH is a promising target for cancer therapy." (PMID 36823188, 2023). "Meanwhile, genes expression in the serine synthesis pathway are upregulated in a variety of cancers, such as increased gene copy number for PHGDH in melanoma and triple negative breast cancer." (PMID 37127605, 2023). "PHGDH catalyses the first rate-limiting step of the serine biosynthesis pathway and is highly expressed in certain cancers, such as triple-negative breast cancers, melanoma, cervical cancer, and gliomas." (PMID 37664062, 2023). "Emerging evidence show that the SSP is altered in various cancer types, especially in the case of the first step, mediated by PHGDH, which is genomically amplified in certain cancers and is considered an oncogene." (PMID 37949226, 2023). "PHGDH upregulation in cancer has been reported to be a consequence of gene amplification or transcriptional upregulation mediated by activating transcription factor 4, nuclear factor erythroid-2-related factor 2, or MYC18,23–25." (PMID 36823188, 2023). "Recently, PHGDH inhibitors exhibited potent anticancer activity against PHGDH-dependent cancers by assays in cancer cell lines and transplanted tumors." (PMID 36803157, 2023). "PHGDH promotes EMT, invasion, and distribution to distant organs by inhibiting the expression of E-cadherin in cancer cells and increasing chemokines in cancer-associated fibroblasts." (PMID 37187454, 2023). "The gene PHGDH codes phosphoglycerate dehydrogenase and has been shown to be overexpressed in several cancers." (PMID 37299011, 2023). "First, we summarize the expression levels of PHGDH mRNA in pan-cancer (33 cancers) from the TCGA database." (PMID 36803157, 2023). "In cancer cells, phosphoglycerate triphosphate, a product of glycolysis, can generate phosphopyruvate by having phosphoglycerate dehydrogenase (PHGDH) and NADPH participate in the reaction process." (PMID 36994237, 2023). "PHGDH (Phosphoglycerate Dehydrogenase) is the first branch enzyme in the serine biosynthetic pathway and plays a vital role in several cancers." (PMID 36803157, 2023).
cancer (continued). "The serine synthesis pathway has been described to be essential for the progression of several types of tumors, and the development of PHGDH inhibitors has emerged as a promising cancer therapy." (PMID 37880317, 2023). "Some small molecule inhibitors targeting PHGDH in PHGDH-dependent cancer cells have been successfully developed and verified in vitro." (PMID 37664062, 2023). "For example, PHGDH supports the rapid growth and uncontrolled spread of a variety of cancers by catalyzing the first step reaction of serine biosynthesis." (PMID 35265615, 2022). "While some cancers acquire amplification or overexpression of PHGDH, the first and rate-limiting step in this pathway, other types of cancers activate oncogenes such as MYC, MDM2, KRAS, and NRF2, leading to increased SSP enzyme expression." (PMID 35316216, 2022). "PHGDH attaches importance to serine biosynthesis in cancer cells and maintaining mitochondrial redox homeostasis." (PMID 36105480, 2022). "We observe that increased serine de novo synthesis (SSP) supports mitochondrial serine catabolism and inhibition of SSP using the competitive PHGDH-inhibitor BI-4916 reduces cancer cell migration." (PMID 35577770, 2022). "The alternative choice is to use low-serine diet or PHGDH inhibitors, which appears promising in preclinical mouse models, yet remains to be exploited for therapeutic benefit in patients with cancer." (PMID 35178349, 2022). "The same paradox exists in several types of cancer cells where inhibition of PHGDH and de novo serine biosynthesis when environmental serine is abundant impairs cancer cell proliferation." (PMID 35115503, 2022). "Another pathway that is activated by RE and involved in the regulation of protein synthesis and muscle hypertrophy is the cancer-like reprogramming inducing the synthesis of serine and glycine via PHGDH." (PMID 35629949, 2022). "This study has identified natural inhibitors of PHGDH for the development of safer and selective cancer therapeutics." (PMID 36144843, 2022). "As the first step rate-limiting enzyme in the serine biosynthetic pathway, PHGDH promotes cancer cell proliferation through overexpression in various cancers." (PMID 36238299, 2022). "Studies have demonstrated that the effect of inhibition of PHGDH in cancer cells cannot be fully rescued by extracellular serine alone, suggesting that these tumors depend on other intermediate products of the SBP." (PMID 36276057, 2022). "A number of tumor entities harbor PHGDH overexpression or IDH1 mutations and the subsequent changes in cancer metabolism can be targeted." (PMID 35635656, 2022). "In contrast to other cancers, the combination of cisplatin and PHGDH inhibitors (NCT-503 or CBR-5884) reduced cisplatin-induced DNA damage in gastric cancer cells." (PMID 35011702, 2022). "Serine is a central hub of cancer metabolism, and PHGDH was seen to be the first rate-limiting step in the serine biosynthetic pathway." (PMID 36147463, 2022). "Knockdown of PHGDH in an in-vivo mouse model played a significant role in the reduction of cancer proliferation and prolonged the survival of the tumor-bearing animal suggesting that PHGDH inhibition have the potential to halt the growth of tumors." (PMID 36144843, 2022). "c-Myc also upregulates SHMT2 under hypoxia, and both the SHMT2 and PHGDH enzymes are positively correlated with each other in cancers such as breast cancer and neuroblastoma." (PMID 36613455, 2022). "PHGDH expression is high in both OS and ES, and high PHGDH correlates with poor survival in both of these cancers, suggesting a clear dependency on the SBP." (PMID 36276057, 2022). "A variety of cancers highly express 3-phosphoglycerate dehydrogenase (PHGDH), the enzyme responsible for de novo serine biosynthesis." (PMID 36059650, 2022). "The PHGDH expression levels in specific subtypes of cancer, such as triple-negative breast cancer or estrogen-receptor-negative cancers, are upregulated." (PMID 36613455, 2022).
cancer (continued). "PHGDH has been reported to be overexpressed in different types of cancers and emerged as a novel target for cancer therapeutics." (PMID 36144843, 2022). "For example, in bladder cancer, compared to individual agents, PHGDH inhibition promotes gemcitabine/cisplatin-induced antitumor effects by suppressing serine biosynthesis and inhibiting cancer cell viability." (PMID 36699468, 2022). "Of note, SG dependency has been reported in cancer and SG deprivation and PHGDH inhibition have been shown to reduce tumor growth." (PMID 35565242, 2022). "PHGDH is upregulated in multiple tumor types, inhibiting tumor-cell proliferation, suggesting utility as a therapeutic target for cancer." (PMID 35344765, 2022). "The enzyme of serine biosynthesis, phosphoglycerate dehydrogenase (PHGDH) is overexpressed in various types of cancer." (PMID 35903445, 2022). "Preclinically, inhibitors of biosynthetic enzymes, such as the SBP enzyme PHGDH are under development for a wide array of cancers, and drugs to target amino acid transporters, such as LAT1 (SLC7A5), are also being explored." (PMID 36276057, 2022). "Augmented de novo serine synthesis activity is increasingly apparent in distinct types of cancers and has mainly sparked interest by investigation of phosphoglycerate dehydrogenase (PHGDH)." (PMID 36291844, 2022). "The role played by PHGDH in BCa was analyzed by determining its expression in cancer and adjacent tissues of BCa patients by IHC." (PMID 36147463, 2022). "Some cancer cells have demonstrated increased de novo serine synthesis through upregulation of PHGDH indicating their survival depends on the sustainable supply of serine." (PMID 35216362, 2022). "Further investigation into the dependence of cancer cells on extracellular serine combined with the development of clinical drugs targeting PHGDH will undoubtedly lead to exciting opportunities in the field of cancer research." (PMID 36291844, 2022). "PHGDH mutants can result in neurological symptoms such as impaired motor function, and its overexpression can promote proliferation and invasion of cancer cells such as HCC." (PMID 37008043, 2022). "Phosphoglycerate dehydrogenase (PHGDH) plays an essential role in cancer-specific metabolic reprogramming." (PMID 35057823, 2022). "As already reported for other cancer cell types under serine starvation, we observed that PHGDH re-expression was regulated at the transcriptional level following ATF4 upregulation at day 4, in serine/glycine-free medium." (PMID 35931688, 2022). "Researchers have observed the flux into this serine biosynthetic pathway through the amplification or upregulation of the PHGDH expression in many cancers." (PMID 36613455, 2022). "The key SSP enzymes PHGDH, PSAT1, and PSPH are significantly overexpressed in a variety of cancers and are associated with poor patient outcomes." (PMID 36699468, 2022). "Enhanced serine production by PHGDH helps tumor growth and is considered as a pattern of cancer metabolism." (PMID 36319669, 2022). "PHGDH is a key enzyme in serine biosynthesis pathway, which plays a key role in serine biosynthesis and mitochondrial redox homeostasis in cancer cells." (PMID 34178629, 2021). "PHGDH is overexpressed in many cancers, either via gene copy-number gain, or transcriptional upregulation mediated via activation of transcription factor 4 (ATF4)." (PMID 33397437, 2021). "The serine synthesis during cancer progression was suppressed when PHGDH went through Parkin-related ubiquitination and degradation." (PMID 34350460, 2021). "Guo’s group extracted a derivative from Aspergillus flavus that was selectively toxic to phosphoglycerate dehydrogenase (PHGDH)-dependent cancer cells." (PMID 34660543, 2021). "Posttranslational regulation via proteasomal degradation is also responsible for PHGDH expression in some cancers." (PMID 34178629, 2021).